BRAF (B-Raf proto-oncogene, serine/threonine kinase)
Diseases named in the same sentence as BRAF in open-access papers (continued):
Sharing a sentence is not in itself a finding about the gene and the disease.
melanoma (continued). "Just as medical oncologists have found subtypes of melanoma that are more sensitive to some systemic therapies than others (e.g., BRAF-mutant), the challenge for radiation oncologists is to find which melanomas are more radiosensitive than others and why." (PMID 39682138, 2024). "We present a case of a 50-year-old Caucasian female who was diagnosed with cancer therapy-related cardiac dysfunction caused by combined BRAF and MEK inhibition in the treatment of malignant melanoma." (PMID 39583362, 2024). "Targeted therapy led to high infiltration of TNFα-expressing TAMs in BRAF-mutant melanoma patients and in melanoma allografts." (PMID 38942020, 2024). "We also tested two lines with distinct drug sensitivities based on alternative genomic contexts (one BRAF mutant melanoma (A375) sensitive to RAF inhibition and one KRAS wild type colorectal cancer (LIM1215) sensitive to EGFR inhibition)." (PMID 38822082, 2024). "In this project, we demonstrated that MEK inhibition was insufficient to induce apoptosis in BRAF WT melanoma cell cultures in vitro." (PMID 38263136, 2024). "Patients with BRAF-mutant melanomas have historically demonstrated an initial benefit from the pharmacological inhibition of mutant BRAF and/or MEK." (PMID 38732242, 2024). "The combination of BRAF inhibitors and MEK inhibitors has significantly enhanced survival in patients with BRAF‐mutant melanoma and has shown some efficacy in treating MBM." (PMID 39399646, 2024). "Currently, the combination therapy of BRAF and MEK inhibitors is being used to treat BRAF-mutated melanoma, resulting in swift but only partial responses in many cases." (PMID 39202970, 2024). "Such a mechanism immediately offers an explanation of the inherent efficacy issues of BRAFi treatment in BRAF-mutant melanoma." (PMID 39001489, 2024). "POLARIS (phase 2 [ph2]; NCT03911869) evaluated encorafenib (BRAF inhibitor) in combination with binimetinib (MEK1/2 inhibitor) in BRAF/MEK inhibitor-naïve patients with BRAF V600-mutant melanoma with asymptomatic brain metastases." (PMID 38725995, 2024). "The EGFR-SFK-STAT3 signaling cascade plays a crucial role in the development of resistance to BRAF inhibitors in melanoma cells." (PMID 38534309, 2024). "Evaluating of these structures containing siRNA (lipoplexes) on melanoma cells indicated that apoptosis was increased as a result of the inhibition of B-RAF expression in murine sarcoma viral oncogene homolog B1 (BRAF) cells." (PMID 38698969, 2024). "This showed that the combination persistently inhibited BRAF WT melanoma cells in two-dimensional (2D) in vitro models." (PMID 38263136, 2024). "The approach was applied to 17 stage IV melanoma patients treated with BRAF/MEK inhibitors, followed for up to 28 months." (PMID 38548846, 2024). "With the development of resistance to BRAF inhibitors, ferroptosis plays a role in melanoma cell viability." (PMID 38336727, 2024). "Precisely, MEK inhibitors have been utilized for the treatment of BRAF-mutated melanoma, KRAS/BRAF-mutated colorectal cancer, hepatocellular carcinoma, low-grade serous ovarian cancer, biliary cancers, and metastatic non-small cell lung cancers." (PMID 39728071, 2024). "In melanoma, TERT promoter mutations, MITF, and CTNNB1 were amongst the genes enriched in metastatic vs. primary Class 1 BRAF mutant tumors." (PMID 38275886, 2024). "Cutaneous melanoma is typically managed with surgery and rarely with topical chemotherapy and radiotherapy, whereas systemic checkpoint immunotherapy and BRAF-targeted or MEK-targeted therapies are used in advanced melanoma." (PMID 39274939, 2024). "The BRAF mutant is the most common mutant type of melanoma, accounting for over 60% of all cases, and NRAS and NF1 have also been found as common mutation sites in melanoma." (PMID 39659781, 2024). "The NRAS gene, like BRAF, is a crucial component of the MAPK pathway and is implicated in 15% to 20% of melanoma cases." (PMID 38534742, 2024).
melanoma (continued). "In particular, the combination of the BRAF–MEK inhibitors dabrafenib and trametinib received regulatory approval after demonstrating significant improvements in RFS in stage III melanoma patients with BRAF V600E or V600K mutations." (PMID 38201012, 2024). "Remarkably, treatment of BRAF inhibitor–resistant (BRAFi-R) melanomas with corin promoted resensitization to BRAFi therapy." (PMID 38300709, 2024). "Inhibitors against MEK and BRAF are being developed and utilised, particularly in the context of melanoma." (PMID 38434478, 2024). "We developed and characterized metastatic melanoma cell lines resistant to BRAF and MEK inhibitors (vemurafenib and cobimetinib, respectively)." (PMID 39175042, 2024). "We next examined the clinical relevance of our finding by analyzing RNA sequencing data in a BRAF mutant melanoma patient cohort treated with BRAF and/or MEK inhibitors (BRAFi and MAPKi)." (PMID 38965534, 2024). "The antitumor response in BRAF-inhibitor-based neoadjuvant therapy is correlated to a strong T-cell response against melanoma tumors." (PMID 39682188, 2024). "In parallel to the impaired copper accumulation, knockdown of ATOX1 significantly reduced the cytotoxic effect of trametinib plus CuET in the BRAF WT melanoma cell lines." (PMID 38263136, 2024). "Mutation burden associated with the development of low-CSD melanoma is lower in comparison to that of the high-CSD type, consisting mainly of BRAF V600E mutations." (PMID 39519202, 2024). "Anti-programmed death 1 (PD-1) antibodies, either alone or in combination with an anti-cytotoxic T lymphocyte-associated antigen-4 (CTLA-4) antibody, have been used in the treatment of BRAF-mutant melanoma." (PMID 39336897, 2024). "While our study provides valuable insights into the therapeutic potential of combining RC48 with dabrafenib in HER2-positive and BRAF-mutant melanoma, there are several limitations that should be acknowledged." (PMID 38594618, 2024). "With this method and identification of more markers, melanomas can be monitored more effectively during treatment regiments using BRAF ctDNA levels as an indicator for treatment effectiveness and tolerance." (PMID 39156972, 2024). "Inhibition of polyamine biosynthesis, EIF5A hypusination, or c-Myc suppressed vemurafenib resistance in melanoma cell line models with either acquired or intrinsic resistance against BRAF inhibitors both in vitro and in vivo." (PMID 38965534, 2024). "As the MES phenotype is also associated with resistance to BRAF/MEK inhibitors, which comprise the second common therapy for melanoma patients, discovering drivers of the MES signature is also relevant for improving this therapy approach." (PMID 38561348, 2024). "Several retrospective studies have reported the clinical outcomes of targeted therapies after early discontinuation of BRAF/MEK inhibitors for advanced BRAF V600‐mutant melanoma." (PMID 38358050, 2024). "A 5-year overall survival rate for metastatic melanoma has increased substantially from less than 10% to up to 40–50% based on PD-1-based treatment and targeted agents in BRAF V600-mutant melanoma." (PMID 38594618, 2024). "Currently, three different inhibitors against advanced BRAF-mutant melanoma are clinically approved for therapy: vemurafenib, dabrafenib, and encorafenib." (PMID 38839106, 2024). "A combined classifier thus provides an advantage here, a finding we have already made in predicting BRAF status using H&E, clinical and methylation data in melanoma suggesting that a multi stain based classifier can lead to better generalizability." (PMID 38241314, 2024). "BRAF-mutant melanoma patients with elevated cGAS expression in their melanoma tumors experienced longer PFS than those with lower cGAS expression." (PMID 38473384, 2024). "Pathways enriched between Class 3 vs. Class 1 BRAF mutant CRCs and Class 3 vs. Class 1 BRAF mutant melanomas were overlapping." (PMID 38275886, 2024).
melanoma (continued). "Serum LDH levels have also shown promise in monitoring disease response and predicting PFS and OS rates in patients receiving dabrafenib and trametinib treatment for metastatic BRAF-mutant melanoma." (PMID 39156972, 2024). "This is the case for EGFR-mutant or ALK-rearranged non-small cell lung cancer inhibitors, tucatinib and trastuzumab–deruxtecan for HER2-positive breast cancer and BRAF inhibitors for melanoma." (PMID 38893253, 2024). "Commonly used targeted therapies used in melanoma are BRAF inhibitors like vemurafenib and dabrafenib; MEK inhibitors like trametinib and cobimetinib or C-KIT inhibitors like imatinib and nilotinib." (PMID 39171057, 2024). "We used human melanoma cell lines with different phenotypes demonstrated by diverse degrees of dependence on the overactive BRAF protein." (PMID 38254853, 2024). "Inhibition of this metabolic shift augments the efficacy of anti-PD-1 immunotherapy in a model of BRAF V600E/PTEN − / − mouse melanoma." (PMID 39271499, 2024). "We found that immunotherapy leads to significantly better outcomes than targeted therapy in BRAF-mutant advanced melanoma patients." (PMID 38473384, 2024). "The COMBI-AD trial evaluated the combination of dabrafenib and trametinib versus placebo in patients with BRAF V600E-mutant resected stage III melanomas." (PMID 39123418, 2024). "In a phase I trial, atezolizumab was safe and well tolerated as a first-line monotherapy in patients with advanced BRAF-mutant melanoma, with an ORR and median PSF of 35% and 3.7 months, respectively." (PMID 39081713, 2024). "Using a different approach, we have also identified an additional oncosuppressive miRNA, namely miR-579-3p, that acts as a regulator of progression and resistance to MAPKi in BRAF-mutant melanomas." (PMID 38472212, 2024). "Cisplatin has shown only moderate efficacy in BRAF-mutated melanoma, mainly due to resistance mechanisms driven by the MAPK/ERK pathway, which is constitutively activated in melanoma with BRAFV600E mutation." (PMID 39766280, 2024). "The availability of three approved BRAF-MEK inhibitor regimens gives multiple options of treatment for patients with stage IV BRAF-V600E/K mutant melanoma." (PMID 38201012, 2024). "From biological points of view, early exposure to MAPKi or, alternatively miR-579-3p transfection, induce block of proliferation and trigger senescence programs in BRAF-mutant melanoma cells." (PMID 38472212, 2024). "Only a few studies were focused on the lncRNAs and BRAF gene and were based on melanoma tissue or cell lines." (PMID 39764216, 2024). "In vitro, the patient- and healthy-donor-derived neutrophils exhibited similar protective abilities toward dual BRAF-/MEK-inhibitor-treated melanoma cells after 24 h." (PMID 38730718, 2024). "Despite inducing objective responses in ~50% of melanoma patients, monotherapy using BRAF inhibitors such as vemurafenib, dabrafenib and encorafenib only induce objective responses in ~5% of BRAFV600E metastatic CRCs." (PMID 38429301, 2024). "Overall, in adult participants with BRAF V600-mutant advanced melanoma or other solid tumors, daily doses of encorafenib in combination with binimetinib were generally safe and well-tolerated when co-administered with daily doses of CYP3A inducer modafinil." (PMID 38878209, 2024). "With values closer to zero, the Bliss scores for BRAF V600E/K melanoma lines (mean = 0.10, std = 0.06) show that Belvarafenib and Cobimetinib inhibition is mostly additive." (PMID 39199684, 2024). "Other non-V600 BRAF mutants, which have been reported in up to 14% of melanoma patients, are very rare, and therefore, little is known about their available treatment." (PMID 38732242, 2024). "For example, BRAF inhibition enhances melanoma antigen expression and facilitates T‐cell cytotoxicity, leading to a more favorable TME." (PMID 39184861, 2024). "In some studies, synchronous inhibition of MDM2 and BRAF is more effective than BRAF monotherapy in BRAFV600E-positive melanomas." (PMID 38396916, 2024).
melanoma (continued). "We confirmed these findings with an additional melanoma cell line and the BRAF + MEK inhibitor combination using dabrafenib and trametinib." (PMID 38866016, 2024). "CAFs create stiff stroma with fibronectin-rich matrices, conferring BRAF-inhibitor resistance to melanoma cells via activation of integrin β1/FAK/Src signaling." (PMID 38730588, 2024). "In fact, all genetic mouse models describing tumor suppressive activity of AMBRA1 so far have been generated on a mutated KRAS/BRAF/MAPK signaling background, and mutations of the KRAS/BRAF/MAPK pathway are common in DLBCL, LUAD, and melanoma." (PMID 39617889, 2024). "Here, plasma levels of IL-8, CCL4, osteopontin, LIF and BDNF were determined at baseline (T0), after 2 months of therapy (T2) and, when feasible, at progression (TP), in 70 melanoma patients treated with BRAF and MEK inhibitors." (PMID 39143551, 2024). "In the context of melanoma, preclinical studies indicate that PMCA4, a plasma membrane calcium ATPase, inhibits the migration and metastatic potential of BRAF-mutant melanoma cells." (PMID 38891988, 2024). "Despite the challenges of the TME, TIL therapy has shown notable efficacy among patients with BRAF V600-mutant melanoma, as indicated by the approval of lifileucel as the first TIL therapy for advanced melanoma." (PMID 39336897, 2024). "Notable responses were observed in phase II, with 18% in metastatic colorectal cancer, 42% in anti-BRAF-pretreated melanoma, and 67% in treatment-naïve melanoma." (PMID 39582535, 2024). "BRAF/MEK inhibitors (BRAF/MEKi) have also been shown to prolong the survival of patients with advanced BRAF V600‐mutant melanoma compared with BRAF inhibitor monotherapy." (PMID 38358050, 2024). "Using BRAF and MEK inhibitors (BRAFi/MEKi) has been a cornerstone in treating melanoma, particularly for those with specific genetic mutations like BRAFV600E." (PMID 39582535, 2024). "In this study, we demonstrated the potential role of MAP3K3 in BRAF inhibitor resistance in melanoma cells." (PMID 38622197, 2024). "This demonstrates that activation of the JNK/JUN pathway is crucial for combination therapy-mediated apoptosis induction and cytotoxicity in BRAF WT melanoma cells." (PMID 38263136, 2024). "Combination therapies of BRAF/MEK inhibitors have significantly improved the efficacy of melanoma treatments, with reduced toxicity and longer progression-free survival (PFS) times compared with monotherapies." (PMID 38474231, 2024). "Even though blocking the MAPK pathway with targeted drugs that inhibit BRAF or MEK kinases has been effective in treating melanoma, acquired or up-front therapeutic resistance is commonly observed in patients." (PMID 38383439, 2024). "The Cancer Genome Atlas has proposed a genetic classification of melanoma into four subtypes based on mutations in BRAF, NRAS, NF1 and triple-wild-type melanomas." (PMID 38903495, 2024). "In terms of molecular characteristics, 86 patients (52.7%) displayed BRAF mutation (100% in the TT group vs. 7.4% in the IT group, p < 0.001), while 33 patients exhibited NRAS mutant melanoma (39.5% in the IT group vs. 1.2% in the TT group, p < 0.001)." (PMID 39272953, 2024). "Understanding why some patients do not respond is especially important, as there are now treatment options for those with advanced BRAF-mutant melanomas: currently either immunotherapy or targeted therapies." (PMID 38473384, 2024). "However, the frequency of BRAF-mutated tumors was only 41%, thus lower than the reported which might be explained by the fact that melanoma patients with BRAF mutations have a worse prognosis, thus a higher risk of mortality compared to patients without BRAF mutations." (PMID 38238578, 2024). "RAF1 and BRAF mutations had a higher prevalence in HRASmt melanoma and UC, respectively, whereas NRAS mutations were more prevalent in HRASwt melanoma." (PMID 38672653, 2024).
melanoma (continued). "Dabrafenib is a small-molecule kinase inhibitor used to treat BRAF-mutant (mut) cancers, including melanoma and non–small cell lung cancer." (PMID 38421883, 2024). "The sensitivity of melanoma cells to ferroptosis relies on their enhanced dependence on oxidative phosphorylation (OXPHOS), which is upregulated by BRAF inhibitors in BRAF-mutant melanoma cells, resulting in the accumulation of ROS." (PMID 38336727, 2024). "In BRAF-mutant ecDNA-null melanoma cells, BRAF amplification – primarily via ecDNA formation – developed following Raf/MEK-inhibitor treatment." (PMID 38625562, 2024). "Again, trametinib inhibited MEK1/2 and ERK1/2 phosphorylation in BRAF WT melanoma cells, which remained largely blocked by the combination." (PMID 38263136, 2024). "BRAF mutant melanomas present as thinner tumors, display higher lymphocyte infiltration, and are detected at a younger age but generally in a more advanced stage." (PMID 39126091, 2024). "We observed differences in biology of melanoma cells resistant to monotherapy compared to mixture of BRAF/MEK inhibitors." (PMID 39175042, 2024). "PAK1 is an oncogene that is involved in activation of the MAPK pathway, and has been suggested as a potential target in BRAF–wild type melanomas." (PMID 38758740, 2024). "We found that YAP activity is dependent on MAP3K3 in CDK4/6 inhibitor-resistant breast cancer cells and BRAF inhibitor-resistant melanoma cells." (PMID 38622197, 2024). "Then, current knowledge with respect to melanoma metabolism is described with an emphasis on major crosstalks between melanoma cell metabolism and signaling pathways involved in BRAF-targeted therapy as well as in immune checkpoint inhibition therapies." (PMID 38339003, 2024). "The eIF4F translation initiation complex plays a critical role in melanoma resistance to clinical BRAF and MEK inhibitors." (PMID 39436655, 2024). "For instance, β-caryophyllene, a terpene found in many essential oils, enhanced the anti-melanoma activity of a BRAF inhibitor, vemurafenib." (PMID 38674007, 2024). "BRAF inhibitors, such as vemurafenib and dabrafenib, have demonstrated significant efficacy in treating patients with BRAF-mutant melanoma." (PMID 39229331, 2024). "With the limited benefit of conventional chemotherapeutics and radiation and growing evidence of clinical activity of BRAF inhibitors in other cancer types such as melanoma, these agents have been also investigated for efficacy in thyroid cancer." (PMID 38275291, 2024). "Furthermore, the sensitivity of melanoma cells to ferroptosis has been linked to their dedifferentiation status, with dedifferentiated cells being more susceptible to ferroptosis, suggesting a potential for combined treatment with BRAF inhibitors and ferroptosis inducers." (PMID 39430757, 2024). "Thirteen (19%) and 20 (30%) patients had BRAF V600 mutations and NRAS-mutant melanoma, respectively." (PMID 38956747, 2024). "In the IMspire150 trial, a combination of vemurafenib plus cobimetinib (Vem/Cobi), a BRAF/MEKi, and atezolizumab, an anti‐PD‐L1 antibody, was compared with Vem/Cobi in 514 treatment‐naïve patients with advanced BRAF V600‐mutant melanoma." (PMID 38358050, 2024). "We previously reported that melanoma cells resistant to the BRAF inhibitor vemurafenib (PLX4032) exhibited increased actin stress fiber formation, which promoted YAP nuclear accumulation." (PMID 38622197, 2024). "Trametinib, a MEK inhibitor, was designed for treating resistant BRAF skin melanomas or in combination with BRAF inhibitors in BRAF mutant melanomas." (PMID 39055896, 2024). "Mutated BRAF exerts exquisite control over MITF, which regulates the expression of key cell cycle facilitators, such as CDK2 and CDK4, stimulating melanoma cell proliferation, survival, and phenotype switching from proliferative and invasive states." (PMID 39735251, 2024).